STAT3 (signal transducer and activator of transcription 3)
Diseases named in the same sentence as STAT3 in open-access papers (continued):
Sharing a sentence is not in itself a finding about the gene and the disease.
pancreatic cancer (continued). "Moreover, this compound also inhibited the invasion and migration of pancreatic cancer cells, which has been reported to be implicated with STAT3." (PMID 22348037, 2012). "Several studies have shown that S1PR1-mediated sustaining activation of STAT3 is of critical importance in proliferation and multidirectional differentiation of CSCs, which is closely associated with acquired radioresistance in a variety of malignancies such as pancreatic cancer and glioma." (PMID 35251963, 2022). "In particular, Acvr2b, FoxO1, and STAT3 all had spearman correlations of at least 0.63 with three of these weights indicating that both the transcriptions factors and TGFβ signaling may play a role in pancreatic cancer associated cachexia." (PMID 30513792, 2018). "Interleukin-6 (IL-6) treatment can enhance anoikis resistance by phosphorylating STAT3, while STAT3 inhibitors like piperlongumine can induce anoikis and prevent tumor formation and metastasis in pancreatic cancer models." (PMID 41596231, 2026). "In melanoma and pancreatic cancer cells, silencing STAT3 leads to 70–80% reduction in anoikis resistance." (PMID 41596231, 2026). "Therapeutically, NBL1's dual role (BMP antagonist in pancreatic cancer versus Stat3 activator in OC) highlights the need for tissue-specific strategies." (PMID 41158754, 2026). "Inhibiting STAT3 reduces anoikis resistance and tumor formation in pancreatic cancer models, highlighting its vital role in cancer progression and metastasis." (PMID 41596231, 2026). "STAT3 has been found to be a genetic modifier of TGF-beta-induced EMT in KRAS mutant pancreatic cancer cells." (PMID 41596231, 2026). "Of particular interest in pancreatic cancer is a small-molecule inhibitor called N4 that has shown strong antitumor activity by directly targeting STAT3 activation." (PMID 41596231, 2026). "Signal transducer and activator of transcription 3 (STAT3) plays a critical role in conferring anoikis resistance to pancreatic cancer cells." (PMID 41596231, 2026). "STAT3 is a critical therapeutic target in pancreatic cancer whose activation relies on the concerted phosphorylation of both Tyr705 and Ser727 residues." (PMID 41463025, 2025). "Recent studies have shown that ZIP4 upregulation in pancreatic cancer promotes the IL-6/STAT3 signalling pathway and activates the production of neuropilin-1 and vascular endothelial growth factor (VEGF), thereby enhancing tumour growth and angiogenesis." (PMID 40869403, 2025). "In pancreatic cancer, LIF secreted by CAFs binds to LIFR on the surface of pancreatic cancer cells and then activates the downstream STAT3 signaling pathway to play its biological role in promoting the progression of pancreatic cancer and chemoresistance." (PMID 40751418, 2025). "It has also been shown that IL1RAP contributes to chemoresistance in pancreatic cancer cells, such as resistance to gemcitabine, by activating NF-κB and STAT3 signalling pathways." (PMID 40444099, 2025). "This suggests that SNX10 loss contributes to PDAC progression primarily by activating the ERK and STAT3 pathways, major drivers of cell proliferation and survival in pancreatic cancer." (PMID 40810725, 2025). "Additional coculture experiments using HPSC‐CM, CTHRC1‐knockdown CAFs‐CM, and CTHRC1‐overexpressing CAFs‐CM consistently confirmed CTHRC1's positive regulation of STAT3 activation in pancreatic cancer cells." (PMID 40751418, 2025). "The natural compound Triptolide inhibits Tyr705 phosphorylation of STAT3, suppressing pancreatic cancer growth in tumour xenograft models." (PMID 41463025, 2025). "The expression of the proto-oncogene Kras in the pancreas activates the Stat3/Socs3 signaling pathway, which relies on IL-6 and its downstream signaling pathways, ultimately promoting pancreatic cancer development." (PMID 39981173, 2025).
pancreatic cancer (continued). "Dosch et al36 demonstrated that the human IL-1R1 antagonist anakinra significantly reduced IL-6 levels and inhibited STAT3 activation in pancreatic tumors derived from PKT mice." (PMID 40060615, 2025). "The STAT3 inhibitor STX‐0119 has exhibited cytotoxic effects against various pancreatic cancer cell types, particularly those with low PD‐L1 expression, highlighting its potential therapeutic relevance." (PMID 40166646, 2025). "CTHRC1 in CAFs promotes the growth and metastasis of pancreatic cancer cells through the LIF/STAT3 signaling pathway." (PMID 40751418, 2025). "Research has indicated that high levels of STAT3 activity are commonly observed in many human tumors, including pancreatic cancer." (PMID 40940782, 2025). "We then cocultured HPSC‐CM and CAFs‐CM with pancreatic cancer cells and, after 24 h, extracted the cell proteins to detect the activation of the STAT3 signaling pathway." (PMID 40751418, 2025). "Among the potential downstream effectors, STAT3 has been reported to modulate GPX4 transcription in pancreatic cancer cells." (PMID 41166024, 2025). "The results showed that the phosphorylation level of STAT3 in pancreatic cancer cells was significantly downregulated after adding the LIF inhibitor, and the downregulation became more significant as the inhibitor concentration increased." (PMID 40751418, 2025). "Together, our findings support the identification of a subset of STAT3 target genes useful in identifying tumors with STAT3 dependency and the ability to stratify survival outcomes for patients with pancreatic cancer." (PMID 40701148, 2025). "Our results confirmed that the expression of phosphorylated JAK1 (P-JAK1), phosphorylated JAK2 (P-JAK2), and phosphorylated STAT3 (P-STAT3) was upregulated in pancreatic cancer cells following RBM10 knockdown." (PMID 40740233, 2025). "Rhein sensitizes human pancreatic cancer cells to EGFR inhibitors by inhibiting STAT3, providing an innovative framework for pancreatic cancer treatment, especially in combination with EGFR inhibitors." (PMID 40572668, 2025). "We next asked if STAT3 is necessary for β3 expression on tumor cells in vivo using a spontaneous mouse model of pancreatic cancer." (PMID 40701148, 2025). "It was discovered that noradrenaline enhances the perineural invasion of pancreatic cancer cells in a concentration-dependent manner by activating STAT3 via the βAR/protein kinase A (PKA) signaling pathway." (PMID 40940782, 2025). "The results showed that CTHRC1 knockdown in CAFs significantly downregulated the phosphorylation level of STAT3 and inhibited the activation of the STAT3 signaling pathway in pancreatic cancer cells." (PMID 40751418, 2025). "Using a series of in vitro and in vivo models, we show that STAT3 is required for pancreatic cancer cells to upregulate integrin β3 expression in response to hypoxia or cytokine stimulation, which enhances a cell’s ability to initiate a tumor in vivo." (PMID 40701148, 2025). "And Kaempferide (KF), a Kaempferol derivative, dose-dependently decreased the phosphorylation of JAK1, Src and STAT3 in the pancreatic cancer cell lines." (PMID 40841966, 2025). "Results from another study demonstrates that thiostrepton induces ferroptosis via Stat3/GPX4 axis in pancreatic cancer cells." (PMID 41341590, 2025). "Thereby, following MCPIP1 overexpression and knockdown, we then examined changes in the IL6/JAK/STAT3 axis in pancreatic tumor cells." (PMID 40874680, 2025). "Pancreatic cancer-educated macrophages upregulate CD59 expression on pancreatic cancer cell lines through STAT3 phosphorylation via the IL-6R/STAT3 signaling pathway and protect them from complement-dependent cytotoxicity." (PMID 40370471, 2025). "Pharmacological blockade of macrophage-derived cytokines or direct inhibition of STAT3 in myofibers significantly attenuates muscle atrophy in pancreatic cancer models." (PMID 40704145, 2025).
pancreatic cancer (continued). "Previous studies showed that the APE1 redox domain can activate STAT3 transcriptional function in pancreatic cancer." (PMID 41090323, 2025). "Reg3g promoted pancreatic cancer carcinogenesis via a STAT3 signaling pathway in a murine model of chronic pancreatitis." (PMID 40427186, 2025). "Pancreatic cancer research further suggested that garcinol and its analogs can trigger both apoptosis and pyroptosis, mediated through STAT3 inhibition." (PMID 41303402, 2025). "CCK‐8 proliferation assays and Transwell migration assays were employed to examine the effects of STAT3 inhibition on pancreatic cancer cell proliferation and migratory capacity under CTHRC1‐overexpressing CAFs‐CM stimulation." (PMID 40751418, 2025). "On the other hand, CAFs overexpressing CTHRC1 significantly increased the phosphorylation level of STAT3 in pancreatic cancer cells and promoted the activation of the STAT3 signaling pathway." (PMID 40751418, 2025). "Suppresses the proliferation and metastasis of pancreatic cancer cells by down-regulating the activities of STAT3, NF-κB, and L1CAM." (PMID 41211420, 2025). "To identify lactylated proteins that regulate STAT3 phosphorylation, we conducted proteomics analysis to search for lactylated proteins on both human pancreatic tumor samples (n = 3) and mouse KPC cells." (PMID 39883522, 2025). "In mechanistic studies, RNA sequencing revealed that CTHRC1 promotes the proliferation and migration of pancreatic cancer cells through the LIF‐mediated STAT3 axis." (PMID 40751418, 2025). "This modification activates the STAT3/NF-κB signalling pathway and induces macrophage M2-type polarisation, thereby promoting pancreatic cancer progression." (PMID 41463025, 2025). "Subsequently, CAFs‐CM with CTHRC1 knockdown or overexpression were cocultured with pancreatic cancer cells, and after 24 h, we extracted the cell proteins to detect the activation of the STAT3 signaling pathway." (PMID 40751418, 2025). "A goal of this study was to learn how pancreatic cancer cells hijack specific functions of STAT3 that allow them to respond to stress and inflammation encountered within the tumor microenvironment." (PMID 40701148, 2025). "Our current study demonstrates that in pancreatic cancer, CTHRC1+ CAFs primarily rely on the LIF/STAT3 signaling pathway to promote pancreatic cancer cell growth and metastasis." (PMID 40751418, 2025). "In pancreatic cancer, Sp1 and STAT3 for example, regulate VEGF and beta-FGF (bFGF) gene expression to promote angiogenesis, metastasis, and tumor cell proliferation." (PMID 38464736, 2024). "miR‐199a‐3p in CAA‐derived exosomes contributes to the malignant transformation of pancreatic cancer via the SOCS7/STAT3/SAA1 pathway, suggesting its potential as a biomarker and therapeutic target for PDAC." (PMID 39431622, 2024). "(C) Summary of pancreatic tumor development in nude mice by KPC cells of the indicated STAT3, SMAD4, and TGFBR2 genotypes presented." (PMID 38573819, 2024). "Accordingly, STAT3 was indispensable for IL-22 induced stemness in pancreatic cancer cells, demonstrating the importance of STAT3 in the pathway." (PMID 38464736, 2024). "This further prevented STAT3 dimerization and suppressed tumor growth and metastasis in mouse models of pancreatic cancer, providing the justification for the small molecule inhibitor as a potential therapeutic for PDAC." (PMID 38464736, 2024). "In this study, we demonstrated that exosomal miR‐199a‐3p secreted from CAAs contributes to the malignant transformation of pancreatic cancer cells by promoting the expression of SAA1 via the miR‐199a‐3p/SOCS7/STAT3 pathway." (PMID 39431622, 2024). "In a different study, the anticancer potential of CuB was demonstrated in PANC-1 pancreatic cancer cells through the suppression of Bcl-2, survival expression, and STAT3 activation." (PMID 38397437, 2024).
pancreatic cancer (continued). "In correlation with existing research, pterostilbene demonstrates its ability to alter gene expression, inhibit phosphorylated signal transducer and activator of transcription 3, and reduce tumor growth in pancreatic cancer." (PMID 38414698, 2024). "Motivated by the pivotal role of the STAT3 pathway in pancreatic cancer, we conducted this study to investigate XYA-2’s impact on pancreatic cancer cells and unravel the associated mechanisms." (PMID 38250721, 2024). "Activation of JAK2/STAT3 signaling in pancreatic cancer can lead to tumorigenesis, progression, cancer stem cell maintenance, and treatment resistance." (PMID 37642814, 2024). "From this work it is apparent that a characteristic feature of pancreatic cancer cells is the maintenance of a continuously active form of PKCε, as well as the phosphorylation/activation of its kinase substrate, Stat3." (PMID 38746674, 2024). "Possible pro-apoptotic signaling pathways are linked to the repression of NF-kB, STAT3, JNK, and p38 MAPK stimulation in pancreatic cancer cells." (PMID 38397437, 2024). "In this review, the current knowledge of STAT3 in pancreatic cancer has been summarized, particularly relating to STAT3 activation in cancer cells, cells of the TME, and the state of targeting STAT3 in pre-clinical and clinical trials of PDAC." (PMID 38464736, 2024). "Considering the function of STAT3–ZDHHC20 axis in KRAS mutant pancreatic cancer above, we explore the biological effect of these proteins in the CDX model." (PMID 38821916, 2024). "Pancreatic tumors were detected within 3 weeks following implantation of 104 parental control, STAT3 knockout (KO), SMAD4 KO, or TGFBR2 KO PDAC cells, and there was no statistical difference in tumor latency between the groups." (PMID 38573819, 2024). "STAT3 also plays a role in shaping the pancreatic cancer microenvironment, contributing to tumor progression (Yu, Pardoll & Jove, 2009)." (PMID 38250721, 2024). "Pancreatic cancer derived exosomes containing lncRNA FGD5-AS1 stimulate STAT3 acetylation and transcriptional activity in surrounding monocytes, promoting M2 polarization." (PMID 39200368, 2024). "Whole tumor RNA-seq analysis of STAT3 intact and knockout pancreatic tumors supported these findings." (PMID 38573819, 2024). "The activation of peroxisome proliferator-activated receptor γ also enhanced pancreatic cancer cell invasion and migration through diverse mechanisms involving crosstalk with STAT3." (PMID 38273295, 2024). "This makes STAT3 a highly attractive target for developing targeted therapies for the treatment of pancreatic cancer." (PMID 38464736, 2024). "In the pancreatic cancer model, TLR7 signaling through STAT3 results in loss of PTEN, p16, and cyclin D1, which leads to tumor development." (PMID 38850110, 2024). "Gene expression profiling of pancreatic cancer cells identifies more than 200 genes commonly regulated by STAT3 and oncogenic KRAS." (PMID 38573819, 2024). "Several clinical trials far have focused on targeting STAT3, yet only two have incorporated pancreatic cancer in the scope of study, to date." (PMID 38464736, 2024). "By directly regulating programmed death ligand-1 (PD-L1) gene expression in cancer cells, STAT3 plays a vital role in the generation of immune cold pancreatic tumors." (PMID 38464736, 2024). "Thiostrepton, a natural cyclic oligopeptide, reduces the viability and clonogenicity of pancreatic cancer cell lines and induces ferroptosis via STAT3/GPX4 signaling." (PMID 38918369, 2024). "Our results are in line with a previous report in pancreatic cancer, which showed that STAT3 signaling is activated in FAK unresponsive and recurrent tumors." (PMID 39271958, 2024).
pancreatic cancer (continued). "STAT3 KO mice exhibited near normal pancreatic histology, demonstrating the critical role of STAT3 in oncogenic KRAS pancreatic cancers." (PMID 38464736, 2024). "Studies have shown that Stat3 binds to the promoter region of Gpx4 and activates its transcription, thereby inhibiting ferroptosis in pancreatic cancer cells." (PMID 38803032, 2024). "ALT significantly inhibited constitutively activated STAT3 in pancreatic cancer cells while having minimal effect on the EGFR pathway." (PMID 38397437, 2024). "Activation of the Reg3A gene alters the JAK2/STAT3 pathway in pancreatic cancer cells, which can increase the expression of REG3A gene, forming a positive feedback mechanism to further promote the expression of REG3A in tumor cells." (PMID 37505298, 2024). "The predominant role of STAT3 in pancreatic cancer is the promotion of angiogenesis via enhanced expression of vascular endothelial growth factor." (PMID 39200368, 2024). "We confirmed that miR‐199a‐3p‐mediated SOCS7 silencing significantly enhanced STAT3 phosphorylation in three pancreatic cancer cell lines." (PMID 39431622, 2024). "As a component of regulating the self-renewal of stem cells, as well as cell survival and inflammation, STAT3 serves a significant role in pancreatic cancer." (PMID 38464736, 2024). "SHK promotes PD-L1 degradation and suppresses the immune escape of pancreatic cancer cells by inhibiting the NF-κB/STAT3 and NF-κB/CSN5 signaling pathways." (PMID 39042294, 2024). "The IL-6/JAK2/STAT3 signaling pathway is vividly involved in the pancreatic intraepithelial neoplasia (PanIN) and the development of pancreatic cancer." (PMID 39201692, 2024). "Given the overlap, further study regarding the crosstalk between Sp1 and STAT3 is necessary, particularly in pancreatic cancer." (PMID 38464736, 2024). "Orthotopically implanted pancreatic cancer (pancreatic adenocarcinoma (PDAC)) was treated with STAT3 ASO with immune checkpoint inhibition." (PMID 39886125, 2024). "STAT3 has emerged as a crucial regulator in the pathogenesis of pancreatic cancer, driving key cellular processes that facilitate tumor progression." (PMID 39199647, 2024). "IL-6 activated STAT3 and increased its phosphorylation, thus upregulating matrix metalloproteinase 2 and vascular endothelial growth factor in the pancreatic cancer line Capan-2." (PMID 38273295, 2024). "This indirectly activates the Janus kinase 2 (JAK2)/signal transducer and activator of transcription 3 (STAT3) signaling pathway, allowing pancreatic cancer cells to become more treatment-resistant." (PMID 38911968, 2024). "STAT proteins, particularly STAT3, play important roles in pancreatic cancer, especially pancreatic ductal adenocarcinoma (PDAC), which is the most prevalent histotype." (PMID 38464736, 2024). "Our study demonstrated that KTN inhibits EMT by suppressing STAT3 signaling, which is consistent with previous findings in pancreatic cancer." (PMID 39519023, 2024). "In conclusion, our study highlights the role of CAAs in promoting pancreatic cancer progression through the secretion of miR‐199a‐3p‐enriched exosomes targeting the SOCS7/STAT3/SAA1 pathway." (PMID 39431622, 2024). "IL-6 induces the STAT3 (signal transducer and activator of transcription 3) signaling pathway, resulting in pancreatic cancer cell proliferation." (PMID 38611003, 2024). "Inhibiting JAK2/STAT3 signaling pathway activation was found to decrease pancreatic cancer growth and induce apoptosis both in vivo and in vitro." (PMID 38182570, 2024).